RHOA (ras homolog family member A)
Diseases named in the same sentence as RHOA in open-access papers (continued):
Sharing a sentence is not in itself a finding about the gene and the disease.
cardiac hypertrophy (45 papers, 2012 to 2025). "Transgenic mice expressing high levels of activated RhoA (a GTPase implicated in cardiac hypertrophy) develop lethal ventricular failure." (PMID 37081960, 2023). "The RhoA/ROCK signaling pathway activation is associated with the development of various cardiovascular pathological processes including cardiac hypertrophy, apoptosis as well as systemic and pulmonary hypertension." (PMID 36139129, 2022). "It has been reported that cleavage of ROCK1 and RhoA/ROCK1-Bax signaling promote apoptosis associated with myocardial hypertrophy and heart failure." (PMID 35370759, 2022). "The best studied downstream effectors of RhoA playing a role in cardiac hypertrophy are the two isoforms of the “Rho-associated coiled-coil containing protein kinase” ROCK-1 (ROKβ) and ROCK-2 (ROKα)." (PMID 33906663, 2021). "On one hand, RhoA is associated with induction of pathological cardiac hypertrophy and re-activation of pro-hypertrophic fetal genes; on the other hand, data suggests a cardio-protective role for RhoA by inducing cell survival signaling." (PMID 33906663, 2021). "The AKAP-Lbc-mediated RhoA activation is associated with the development of cardiac hypertrophy and cancer." (PMID 29373579, 2018). "The RhoA/ROCK pathway is associated with myocardial hypertrophy." (PMID 35811723, 2022). "These future studies should result into new therapies for pathological cardiac hypertrophy, by inhibition of detrimental pathways and/or enhancement beneficial signaling pathways downstream of RhoA, which are associated with adaptive hypertrophy or other cardio-protective effects." (PMID 33906663, 2021). "In cardiac myocytes, decreased miR-133 levels during pathological hypertrophy led to increased Ctgf and collagen synthesis and resultant heart failure, and was also associated with increased levels of RhoA, which inhibits axon growth and regeneration, and is involved in cardiac hypertrophy." (PMID 30427927, 2018). "Their study identified a novel signaling pathway for pathological cardiac hypertrophy: m6A-circCDYL-tCDYL-100-REST (RE1-silencing transcription factor)/CDYL-RhoA (Ras homolog family member A)/BNP (brain natriuretic peptide)." (PMID 41181701, 2025). "Glucagon-like peptide one inhibits RhoA expression and reverses cardiac hypertrophy via the cAMP-PKA signaling pathway." (PMID 40969943, 2025). "A recent study using RhoA cKO mice demonstrated that RhoA-mediated mitophagy provides cardioprotection against aging-induced adverse cardiac remodeling, including cardiac hypertrophy, fibrosis, dilation, and contractile dysfunction." (PMID 39122698, 2024). "Mechanistically, RhoA/ROCK signaling has been shown to induce cardiac hypertrophy via AngII-receptor-mediated vasoconstriction, probably facilitated by RhoGEFs expressed in VSMCs (PDZ-RhoGEF, LARG and p115RhoGEF)." (PMID 33906663, 2021). "In mouse, microRNA‐133 has been demonstrated to inhibit cardiac hypertrophy through repressing the translation of RhoA, Cdc42, and NELF‐A mRNA." (PMID 33788376, 2021). "Contrary, upregulation of ANP in NRVCMs has been demonstrated to reduce NFB-/TNF-induced immune responses, highlighting the complex and often ambiguous role of RhoA-activation in the context of cardiac hypertrophy and immune responses." (PMID 33906663, 2021). "Taken together, the modulation of blood pressure and its interrelation with cardiac hypertrophy adds another level of complexity to the manifold RhoA-signaling in the cardiovascular system." (PMID 33906663, 2021). "MiRNA‐133 is decreased in mouse and human models of cardiac hypertrophy 134 through its regulation of the Ras homolog family member A (RhoA) and cell division control protein 42 homolog (Cdc42)." (PMID 29972883, 2018). "Given RhoA/ROCK signalling is one of cardiac hypertrophy 34, fasudil attenuated right ventricular hypertrophy by inhibiting RhoA/ROCK signalling." (PMID 29119680, 2018).
cardiac hypertrophy (continued). "RhoA is expressed in the heart during embryonic development, is down-regulated after birth and re-expressed in cardiac hypertrophy." (PMID 29206857, 2017). "In our previous studies, we find that inhibition of FPPS attenuates angiotensin II-induced cardiac hypertrophy and fibrosis by suppressing RhoA while FPPS and Ras are up-regulated in pressure overload rats." (PMID 28008986, 2016). "Both are involved in cardiac hypertrophy and heart failure 24, 27, and RhoA regulates the endothelial permeability." (PMID 27642643, 2016). "We had demonstrated that overexpression of FPPS can lead to cardiac hypertrophy, fibrosis, and LV dysfunction by RhoA activation." (PMID 28008986, 2016). "The RhoGEF (Rho GTPase guanine-nucleotide-exchange factor) domain of AKAP-Lbc (A-kinase-anchoring protein-Lbc, also known as AKAP13) catalyses nucleotide exchange on RhoA and is involved in the development of cardiac hypertrophy." (PMID 25186459, 2014). "MiR-133 is decreased in mouse and human models of cardiac hypertrophy, and has been shown to inhibit cardiac hypertrophy by targeting RhoA, Cdc42, and Nelf-A/WHSC2." (PMID 22926414, 2012). "However, the direct role of RhoA in the myocardium is rarely studied at present, but it is certain that RhoA directly or indirectly regulates the death and survival of myocardial cells, myocardial hypertrophy, and fibrosis after ischemic injury." (PMID 35273164, 2022). "In respect to the functions of RhoA in cardiomyocytes, the effects of this inhibitor on heart function in cardiac hypertrophy or other heart diseases could be subject of future research." (PMID 33906663, 2021). "These contrasting results regarding RhoA/ROCK signaling in cardiac hypertrophy may be explained by differences in the states of hypertrophy, i.e. compensatory or pathological hypertrophy." (PMID 33906663, 2021). "Thus, more research focusing on the physiological function of RhoA as well as its distinct role in adaptive and maladaptive cardiac hypertrophy is needed." (PMID 33906663, 2021). "So, dasatinib might also have beneficial effects in cardiac hypertrophy, by reducing RhoA-activation in cardiomyocytes and/or restraining detrimental immune responses correlated with the progression to heart failure." (PMID 33906663, 2021). "Actin cytoskeleton signaling, Ras homolog family member A (RhoA) signaling, integrin signaling, cardiac hypertrophy signaling (enhanced) and vascular endothelial growth factor (VEGF) signaling pathways have been previously reported to be related to cardiac functions." (PMID 31948008, 2020). "We propose that the overexpression of FMN1 found in our study may lead to the activation of RhoA/ROCK signaling pathways implicating further development of cardiac hypertrophy." (PMID 25984239, 2015). "These disease links involving the RhoGEF activity of AKAP-Lbc suggest that inhibitors of the RhoA–AKAP-Lbc interaction may be a worthwhile line of investigation for treatment of cardiac hypertrophy, pulmonary arterial hypertension and possibly for cancers." (PMID 25186459, 2014). "Recently, a novel small molecule, Scaff10-8, was developed, which inhibits the interaction of AKAP-Lbc and RhoA and prevents the AKAP-Lbc-mediated RhoA activation, an event pathologically activated in models of cardiac hypertrophy." (PMID 29461511, 2018). "Increasing evidences have demonstrated that the RhoA-ROCK pathway plays a pivotal role in cardiovascular pathogenesis such as I/R injury, vascular smooth muscle cell (VSMC) proliferation, cardiac hypertrophy, heart failure, and ventricular remodeling." (PMID 25861370, 2015).
cardiac hypertrophy (continued). "RhoA signaling activates ROCK signaling which effects several cardiac cell types leading to altered cardiomyocyte contraction, cardiac gene expression, and protein phosphorylation and subsequently to cardiac hypertrophy and fibrosis." (PMID 37658118, 2023). "Moreover, previous study has highlighted the importance of SC in anti-inflammatory effect under cardiac hypertrophy through inactivating the calcineurin-NFAT2 pathway, a downstream cascade of RhoA-ROCK signaling pathway." (PMID 32240450, 2020). "Thus, it is suggested that RhoA and Ras/ERK systems contribute to the mechanism of cardiac hypertrophy induced by large BP variability in hypertensive heart." (PMID 25544288, 2014). "Simvastatin inhibited the activation of RhoA and RAS/ERK systems and then inhibited cardiac hypertrophy, but not myocardial fibrosis, in SHR+SAD without affecting BP variability." (PMID 25544288, 2014).
endothelial dysfunction (45 papers, 2010 to 2025). In vascular diseases, endothelial dysfunction is a systemic pathological state of the endothelium (the inner lining of blood vessels) and can be broadly defined as an imbalance between vasodilating and vasoconstricting substances produced by (or acting on) the endothelium. "One of the factors associated with endothelial dysfunction leading to aneurysm development is ras homolog family member A (RhoA) pathway activation." (PMID 34884962, 2021). "Our results demonstrated that the S1PR2 antagonist (JTE-013) almost completely blocked endothelial dysfunction and associated fission and dysfunction of mitochondria under HG conditions along with down-regulated HG-promoted expression of RhoA/ROCK1." (PMID 30999892, 2019). "Levels of RhoA and Rho-Kinase are associated with the level of endothelial dysfunction in patients with COPD." (PMID 28100233, 2017). "IL-17 has been linked to RhoA/Rho kinase-mediated endothelial dysfunction in SHRs." (PMID 41254951, 2025). "The RhoA/mDia-1 (mammalian diaphanous homolog-1)/profiling-1 or RhoA/ROCK1 (Rho-associated coiled-coil-containing protein kinase 1) pathways have been shown to be involved in the pathology of DR via triggering microvascular endothelial dysfunction." (PMID 26881246, 2016). "Specifically, RhoA/ROCK signaling contributes to endothelial dysfunction and vascular remodeling by increasing calcium sensitivity, enhancing vasoconstriction, promoting stress fiber reorganization, and inhibiting endothelial nitric oxide synthesis." (PMID 40453665, 2025). "RhoA/ROCK signaling contributes to endothelial dysfunction and vascular remodeling through multiple, interconnected mechanisms." (PMID 41301525, 2025). "Overall, the RhoA/ROCK pathway not only contributes to endothelial dysfunction but also plays a role in endothelial cell activation." (PMID 40453665, 2025). "This review summarises the role of the RhoA/Rho kinase signalling pathway in endothelial dysfunction, the acquisition of the pro‐thrombotic state and vascular ageing." (PMID 38568071, 2024). "This review summarises the role of RhoA/Rho kinase signalling in endothelial dysfunction, thrombosis and vascular aging and its possible role as a promising therapeutic target for the prevention and treatment of CVD in the elderly population." (PMID 38568071, 2024). "eGC degradation- and RhoA-induced cortical stiffening with subsequent endothelial dysfunction were attenuated after administering PMX53." (PMID 39055717, 2024). "Borikova and colleagues reported a marked increase in total RhoA protein levels after the loss of expression of CCM1, CCM2, or CCM3 and demonstrated that knockdown of RhoA effectively reverses endothelial dysfunction caused by CCM deficiency." (PMID 35316220, 2022). "IL-17 is also a potent pro-inflammatory cytokine and activates RhoA/Rho-kinase, leading to endothelial dysfunction." (PMID 35463755, 2022). "Microvascular endothelial dysfunction is due to the RhoA/mDia-1 and RhoA/ROCK1 pathways in which RhoA act as GTPase." (PMID 33564616, 2021). "Cigarette smoke disrupts the endothelial barrier in the lung by increasing ROS, leading to activation of RhoA and endothelial dysfunction." (PMID 31174369, 2019). "The results suggested that the pathway of RhoA/ROCK/NFATc3 contributed to endothelial dysfunction by CIH." (PMID 29641598, 2018). "In conclusion, this study demonstrates that CIH-induced endothelial dysfunction in OSA is mediated by eNOS/NO reduction through RhoA/ROCK/NFATc3 pathway activation." (PMID 29641598, 2018). "Activation of the AGEs–RAGE axis evokes inflammatory responses through several signaling pathways, resulting in endothelial dysfunction, among which the RhoA/ROCK/moesin pathway plays a critical role in vascular barrier dysfunction." (PMID 29867568, 2018). "The interaction between RhoA/Rho-kinase pathway and eNOS/NO/cGMP pathway in endothelial dysfunction in the pathogenesis of COPD needs to be further studied." (PMID 24303177, 2013).
endothelial dysfunction (continued). "Taking together, this study provides direct evidences to show that the up-regulation of RhoA activity is involved in AGE-induced endothelial dysfunction." (PMID 22251897, 2012). "Recent studies also found that RhoA/ROCK-dependent moesin phosphorylation involved in the advanced glycation end products-mediated endothelial dysfunction." (PMID 22694757, 2012). "Inhibition of the RhoA/ROCK pathway can prevent endothelial dysfunction in a variety of pathological conditions." (PMID 21264178, 2010). "In this issue, Dr. Caldwell from the Department of Pharmacology and Toxicology, Medical College of Georgia, has reviewed the role of RhoA/Rho kinase (ROCK) pathway in endothelial dysfunction." (PMID 21264178, 2010). "Similarly, up-regulation of RhoA in a hyperglycemic state aggravates endothelial dysfunction and increases endothelial permeability through stress fiber formation, focal adhesion and cell contraction." (PMID 39080630, 2024). "The findings reviewed here suggest that RhoA/Rho kinase pathway activity in endothelial dysfunction is highly relevant to frailty syndrome and could provide a promising route to the development of therapeutic interventions to prevent vascular aging." (PMID 38568071, 2024). "Nonetheless, the exact role of RhoA/ROCK in endothelial dysfunction induced by P. gingivalis is still unknown and needs further investigation." (PMID 37278388, 2023). "Furthermore, Y-27632 improved aortic remodeling, fibrosis, endothelial dysfunction, superior mesenteric artery endothelial injury, left ventricular dysfunction and cardiac fibrosis in mice by weakening the activation of the RhoA/ROCK pathway." (PMID 35811723, 2022). "Oxidative stress, endothelial dysfunction, and low-grade chronic inflammation contribute to the pathogenesis of coronary artery syndrome, leading to increased coronary smooth muscle Ca2+ sensitivity through RhoA/ROCK activation and resultant hypercontraction." (PMID 31174369, 2019). "In the study, we imitated OSA using a rat model of CIH to investigate the role of ROCK, and detected whether CIH might affect RhoA/ROCK/NFATc3 mediated endothelial dysfunction in aortas." (PMID 29641598, 2018). "Since small GTPase RhoA is known to play a crucial role in endothelial dysfunction, through down-regulation of eNOS and its phosphorylation, we evaluated whether the functional inhibition of miR-16 inhibits its activity." (PMID 29335599, 2018). "RhoA is activated by CS and participates in subsequent endothelial dysfunction." (PMID 29326688, 2017). "The RhoA/Rho-kinase pathway which is upregulated in patients with COPD may also result in endothelial dysfunction." (PMID 28100233, 2017). "Similarly, pharmacological and genetic inhibition of ROCK, the down-stream kinase of RhoA, showed similar inhibitory effects on arginase activity and endothelial dysfunction in atherosclerotic, diabetic, and angiotensin-II-induced hypertensive animal models." (PMID 23781221, 2013). "This RhoA/ROCK -dependent moesin phosphorylation regulates AGE-induced endothelial dysfunction." (PMID 22251897, 2012). "The RhoA/Rho kinase pathway is a crucial signalling component in the vascular system and particularly in ECs and has been extensively studied in diverse pathophysiological settings, including endothelial dysfunction, impaired angiogenesis, inflammation and apoptosis." (PMID 38568071, 2024). "IL-17 may induce endothelial dysfunction through activating RhoA/Rho-kinase." (PMID 36009796, 2022). "The activation of RhoA/Rho-kinase pathway plays important roles in regulating many cell functions, such as proliferation, migration, apoptosis, contraction, as well as gene expression and endothelial dysfunction, which can be involved in the pathogenesis of COPD." (PMID 24303177, 2013). "Generally, RhoA/ROCK1 pathway activation leads to the progression of cardiovascular diseases through inflammation, endothelial dysfunctions, VSMCs contraction, proliferation and migration." (PMID 37278388, 2023).
endothelial dysfunction (continued). "In endothelial cells, UCA1 formed a ternary complex with USP14 and PFN1, prolonged the half-life of the PFN1 protein, and subsequently activated the RhoA/ROCK pathway to produce excess ROS and induce endothelial dysfunction." (PMID 36160709, 2022). "A previous study found that anagliptin, a dipeptidyl peptidase IV (DPP-4) inhibitor, suppresses IH by preventing endothelial dysfunction and regulating SOD-1/RhoA/Jun N-terminal kinase- (JNK-) mediated EC migration following balloon-induced injury." (PMID 35450412, 2022). "This study showed the presence of endothelial dysfunction in pulmonary arteries of patients with COPD where downregulation of eNOS activity and upregulation of RhoA/Rho-kinase activity also occurred." (PMID 24303177, 2013). "Up-regulation of RhoA and ROCK contributes to AGE-induced endothelial dysfunction." (PMID 29867568, 2018). "Some studies have demonstrated that NFATc3 was related to pulmonary hypertension induced by CIH in mice, however, the mechanism by which RhoA/ROCK/NFATc3 mediates CIH-induced endothelial dysfunction has not been fully clarified." (PMID 29641598, 2018). "However, this induction of endothelial dysfunction and antiangiogenic effects by active RhoA seems to be independent of its downstream effectors, ROCK and LIMK." (PMID 38568071, 2024). "In addition to the well-established thrombin-induced RhoA/MLC pathway, we defined a role for p38 MAPK signaling in thrombin-stimulated endothelial dysfunction that is independent of the RhoA/MLC pathway." (PMID 35257745, 2022).